RET (ret proto-oncogene)
Diseases named in the same sentence as RET in open-access papers (continued):
Sharing a sentence is not in itself a finding about the gene and the disease.
cancer (continued). "Moreover, numerous oncogenic drivers (ALK, BRAF, EGFR, MET, NRG1, NTRK1/2/3, RET, and ROS1) involved in sole reciprocal fusions were found in those cancers." (PMID 39254060, 2024). "These oncogenes are observed in NSCLC and other cancer types, but no murine models and limited RET+ and NTRK+ human cell lines exist." (PMID 37470475, 2023). "VGFR1, KIT, FGFR1 and RET were expressed at similar levels in healthy and non-tumorous (histologically normal) livers from cancer patients." (PMID 36890818, 2023). "The relative abundance of RTKs was broadly similar in samples from healthy individuals when compared to non-tumorous tissue taken from liver of cancer patients, with RET being the most abundant." (PMID 36890818, 2023). "While this new approach allowed us to confirm the difference in RET dependency between SCN HI and LO cell lines, the ZBTB7A dependency scores alone failed to segregate cell lines into two groups, probably due to its counter roles in cancer." (PMID 37065756, 2023). "RET and NTRK inhibitors are among the first tissue agnostic drugs that could be used in cancer patients with RET and NTRK gene rearrangements, regardless of the pathomorphological type of cancer." (PMID 37509393, 2023). "This, combined with challenges related to drug tolerance due to lack of specificity, has made the need for selective RET inhibitors for the treatment of RET-driven cancers a growing clinical interest." (PMID 36918928, 2023). "In a previous study, BRAF and RET/PTC1 rearrangement and TERT promoter mutations were associated with more aggressive cancers than malignancies without one of these mutations." (PMID 37370711, 2023). "This study showed that selpercatinib use as frontline therapy is associated with improved outcomes versus standard therapies in patients with RET-altered cancers in the lung, thyroid, and other non-lung, non-thyroid organs in the body." (PMID 38201566, 2023). "Studies presenting long-term follow-up of patients with RET fusion-positive carcinoma are almost absent." (PMID 37882481, 2023). "While regorafenib is currently in numerous clinical trials for use in various cancer types (ClinicalTrials.gov), it has not entered trials for use in RET-altered cancers." (PMID 35957881, 2022). "We tested the top prediction from Problem 1 in the Drosophila RETM955 model system of RET-driven cancer but did not observe bioactivity." (PMID 34520464, 2021). "NRAS mutations have also been identified as resistance mechanisms using patient-derived cell line models harboring RET and ROS1 gene fusions, further supporting the idea that cancers often develop resistance using a somewhat finite group of oncogenes following TKI treatment." (PMID 34642436, 2021). "No RET/PTC rearrangements were found in malignant tumours and one RET/PTC3 was detected in a benign nodule." (PMID 32638211, 2021). "In human pancreatic adenocarcinoma (MiaPaCa-2) cells, GDNF binds to its receptor GFRalpha1, activates the RET co-receptor, and promotes mitogen-activated protein kinase (MAPK) signaling to induce cancer cell migration towards nerve in vitro and animal models of PNI." (PMID 34885121, 2021). "Several multi-target TKIs targeting RET are approved by the FDA for cancer therapy and non-oncologic disease treatment." (PMID 32984034, 2020). "This substitution is close to the RET R693H mutant we studied, which reflects the importance of variations in this domain in cancer, while the allosteric mechanisms are not yet known." (PMID 32293499, 2020). "The discovery of driver oncogenes with aberrant tyrosine kinase activation, such as ALK, ROS1, RET, or NTRK1 gene rearrangement in cancers, continues to change the therapeutic strategies and treatment regimens accompanied with the development of targeted therapies." (PMID 32871626, 2020).
cancer (continued). "We further examine those perturbed cancer pathways that were specifically proposed in the study that generated the data examined here, as well as others that are clinically actionable, i.e., ErbB, PI3K-Akt, and RET." (PMID 33013452, 2020). "Although RET is frequently undetectable in some human cancers, including OS 39, we found an overt accumulation of the RET protein without a change its mRNA level in response to prolonged treatment with the proteasome inhibitor BTZ." (PMID 31534554, 2019). "Relatives who are RET negative will not develop MTC, whereas RET-positive subjects are at risk to develop the cancer and must be followed and treated." (PMID 31510104, 2019). "The identification of fusion driver oncogenes with aberrant tyrosine kinase activation, such as ALK, ROS1, RET, or NTRK1 rearrangement in cancers, is largely changing therapeutic strategies accompanied with the development of targeted therapies, especially potent TKIs." (PMID 31399568, 2019). "In these samples, hierarchical clustering based on the expression of 1498 metabolic genes annotated in KEGG database showed the distinct expression pattern between EGFR-, FGFR- and RET-activated tumors, suggesting the distinct metabolic phenotypes in oncogenic RTK-driven cancer." (PMID 31221965, 2019). "In line with previous observations, genes involved in cancer development were represented on Bs of four studied species: red fox (KIT), Chinese raccoon dog (ENPP1, GNAS, HMGCR, KDR, RET), brocket deer (BCL6, RASA1, RET), and Korean field mouse (JAK3)." (PMID 30103445, 2018). "Samples with fusions involving oncogenes, such as EGFR, ERBB2, and RET, showed increased expression of those genes relative to samples without fusions across cancer types." (PMID 29617662, 2018). "Nearly 80% or more of SNVs in FLT3, PDGFRA, PGR, and RET were not expressed among all cancer patients." (PMID 29721196, 2018). "As NIFTP is by definition a borderline tumor, any tumors with cancer-specific mutations such as BRAFV600E, RET/PTC rearrangements, and TERT promoter mutations should not be diagnosed as NIFTP." (PMID 29476382, 2018). "Importantly, at the observed time-window of age, the more aggressive solid variant of PTC was present in 3 out of 14 carcinomas (21%) in RET/PTC1;Patz1+/− mice, compared with 1 out of 12 carcinomas (8%) in RET/PTC1TG;Patz1+/+ mice." (PMID 29584698, 2018). "BT13 is a short-living compound having lower efficacy than GDNF (for example its activated luciferase in screening assay by maximum 11.6 fold, whereas GDNF—by 50–100 folds, thus, it is unlikely to promote cancers as a result of RET activation." (PMID 28680400, 2017). "The uncovered regulation between RET, miR-182 and HES1 clearly points toward new prognostic and therapeutic options by using components of the RET-NF-κB/miR-182-HES1/Notch1 axis as potential key targets to restrict cancer progression." (PMID 28122586, 2017). "Apatinib exerted its anti-cancer effect not only via cytotoxicity, but also via inhibition of migration and invasion by suppressing RET/Src signaling pathway, supporting a potential role for Apatinib in the treatment of KIF5B-RET driven tumors." (PMID 27494860, 2016). "The in-vitro studies suggest low dose regorafenib potently suppresses RET fusion-positive cancer cells but has minimal inhibitory activity in RET fusion-negative CRC cells." (PMID 26078337, 2015). "Multiple RET kinase inhibitors were cytotoxic to RET fusion kinase positive cancer cells and not RET fusion kinase negative CRC cells." (PMID 26078337, 2015). "After splitting up the tumors according to genotype cluster (i.e. cluster 1: SDHx- and VHL-related PCC/PGL; cluster 2: RET-, NF1-, and TMEM127-related tumors), malignant tumors (n = 24) clustered more often in genotype cluster 1 (P<0.0001), compared to benign tumors (n = 33)." (PMID 25794004, 2015).
cancer (continued). "Previous reports state that RET binds to the FERM domain of FAK, an interaction that results in transactivation of both proteins, and that RET is degraded by autophagy in cancer cells with altered/reduced FAK signalling, preventing RET binding to FAK at focal adhesions." (PMID 24467886, 2014). "On the basis of their pathological features and of the fact that a large proportion of them demonstrate RET-PTC translocations, these cancers are considered as similar to classical sporadic papillary carcinomas, although molecular alterations differ between both tumours." (PMID 15812549, 2005). "Additionally, BAM-secreted GDNF promotes cancer cell survival in the leptomeninges, suggesting that inhibitors of the GDNF signaling pathway, such as RET inhibitors, could improve treatment outcomes." (PMID 41219968, 2025). "Sequencing results showed that MET, EGFR, KMT2B and RET gene were mutated in LGFM, and KMT2B gene had cancer promoting effect, but there was no literature report in LGFM, which may be of certain significance for the diagnosis and treatment of LGFM." (PMID 38347522, 2024). "Given the burgeoning approvals and implications in the tissue agnostic arena, many patients with RET fusion positive cancers may present with non-measurable disease on plain CT scans." (PMID 39272672, 2024). "Furthermore, we performed CIC activities analysis and found that most of the steps, including priming and activation (Step 3) as well as trafficking of immune cells to tumors (Step 4) were activated in PTC with RET-MT or BRAF-MT, whereas recognition of cancer cells (Step 6) was suppressed." (PMID 38734621, 2024). "However, whether used in monotherapy or combination with chemotherapy, ICIs appear to be ineffective in EGFR, ALK, RET, and HER2 driver gene‐positive cancers." (PMID 39184861, 2024). "This could explain the diverse effects of adefovir on other cell types that are not driven by RET-related cancer, RET/PTC1, and RET M918T." (PMID 37046823, 2023). "It has yet to be proven whether RET in-frame and frameshift deletions in non-MTC and non-PHEO cancers are pathogenic." (PMID 36091144, 2022). "In addition, the use of Drosophila for cancer modeling allows fast molecular profiling and toxicity evaluation that, for example, recently led to the identification of AD80 and AD81 as polypharmacological agents for RET-driven tumors." (PMID 33591981, 2021). "Patients with cancers with mutations in RAS (HRAS, KRAS, and NRAS) had an overall response rate of 31% compared to a response rate of 32% in patients with RET-mutation positive disease with no survival benefit observed in patients with tumors lacking both RET and RAS mutations." (PMID 34489865, 2021). "RET inhibition may therefore be an attractive therapeutic target in cancer as an immune modulator irrespective of the presence of RET-activating mutations." (PMID 33020210, 2020). "Interestingly, ROS1 and BRD4 KGFs occur at four different breakpoint sites; conversely, ALK and RET are found rearranged using the same breakpoint in different cancer cell line models, regardless of the cancer type context." (PMID 33257674, 2020). "However, RET expression by immune cells in cancer has, to the best of our knowledge, not been previously assessed." (PMID 33020210, 2020).
cancer (continued). "During tumorigenesis, cancer cells secrete Colony Stimulating Factor (CSF–1) to recruit macrophages; in turn, recruited macrophages release glial derived neurotrophic factor (GDNF) that activates RET (REarranged during Transfection) on cancer cells to promote cancer migration and nerve invasion." (PMID 31248001, 2019). "Moreover, although the expression of ALK and ROS1 at the C-terminus was very limited in all fusion-negative cancer cells, the expression or phosphorylation of C-terminal RET was markedly elevated in 2 of the 36 RET fusion–negative cancer cells." (PMID 30943926, 2019). "Once GDNF/GFRA1/RET makes a complex, it activates various signaling pathways, such as RAS/MAPK, PI3K/Akt and PLCγ pathway, which contribute to cell proliferation, adhesion, migration, differentiation and survival and which contribute to the pathogenesis of both cancer and neuronal disease." (PMID 29617307, 2018). "Not surprisingly, in cancer cells activation of RET oncogenic signaling, which can be induced and enhanced by SH2B1, can override growth suppressor (RET inhibitors) activities and stimulate cell cycle progression and further potentiates the neoplastic transformation." (PMID 30202243, 2018). "In order to verify whether the RET negative tumoral tissues belonging to cases with other RET positive tissues were false negative due to a low percentage of cancer cells in the sample, we evaluated the prevalence of tumoral cells in the tissue samples." (PMID 29515777, 2018). "Finally, as reported in Asian studies, ROS1 and RET fusion genes were found in large cell and not otherwise specified carcinoma highlighting that the screening should not be restricted to adenocarcinoma." (PMID 28881815, 2017). "Notably, RET fusion-positive cancer cells, but not RET fusion-negative cancer cells, had similar exquisite sensitivity to regorafenib, vandetanib and lenvatinib, which share RET and VEGFR kinases as the only common molecular targets." (PMID 26078337, 2015). "Since we observe here that perturbed DNA topoisomerase I and II activity can effect fragile site breakage at the RET oncogene, more work should be done to investigate the role of topoisomerase poisons and fragile sites in the formation of secondary PTC tumors and other cancers." (PMID 24040417, 2013). "For example, chromosomal rearrangements of the tyrosine kinase proto-oncogenes RET, the RET/PTC3 in particular, found in high proportion in papillary TC (PTC) of patients exposed during childhood and adolescence, were discussed as possible markers of radiogenic cancer." (PMID 22175034, 2012). "Recently, XB130 was found in different cancer cells in the absence of RET/PTC." (PMID 22928011, 2012). "Our results suggest that the strategy of sequential TKI treatment developed for other oncogene-driven cancers may not be as broadly effective in RET-driven cancers, possibly due to the selectivity and potency of currently available purpose-built RET inhibitors." (PMID 35304457, 2022). "This phenomenon is thought to occur since this study is performed in RET fusion-positive patient group in NSCLC and it might mean that RET fusion partners in NSCLC preferably contains the longer transcript since it is more aggressive and evolutionarily selected during cancer progression." (PMID 27150058, 2016). "The use of two or three markers might be more relevant than just one as recently shown on a series of 37 fine-needle aspiration biopsies using a panel of markers consisting of galectin-3, HBME1 and RET, where none of the 20 malignant tumours was negative for this panel." (PMID 16251880, 2005). "In oncogene-addicted cancers (HER2-mutant cancer, oncogene-driven EGFR-positive, ALK-positive, or RET-positive NSCLC), current studies do not encourage the use of immune checkpoint inhibitors, with the exception of KRAS-mutated cancers." (PMID 36865093, 2023).
cancer (continued). "For the cancer types that performed the worst, liver hepatocellular carcinoma included none of the used oncogenes (AR, KLF4, PDGFRA, and RET) or tumor suppressors (BRCA2, CDKN2A, and TSC1) that were linked to it." (PMID 31900418, 2020). "This disparity may be due to the higher percentage of cancer documented in American RAS-mutated indeterminate nodules, possibly because the Bethesda and SIAPEC classifications do not perfectly overlap, and/or because our panel did not include RET/PTC and PAX8/PPARG rearrangement analysis." (PMID 29085338, 2017). "Using two different primer pairs that either bound within the RET kinase domain or flanked the CCDC6-RET fusion site, we confirmed by quantitative PCR that Lc2/ad cancer cells, but not several KRAS wildtype and mutant CRC cells, harbored the CCDC6-RET fusion kinase." (PMID 26078337, 2015). "The search for genetic alterations for the identification of malignancy has low sensitivity, since numerous cancer samples do not bear any of these genetic alterations, and low specificity, since benign adenoma shares genetic lesions (RAS, PPARg and RET/PTC) with cancer." (PMID 23946782, 2013). "Cancer cell migration induced by macrophage-derived GDNF depends on GFRα1 co-receptor and RET, as demonstrated by the inhibitory effect observed in knock down experiments with cells lacking GFRα1 co-receptor and the use of RET inhibitor (pyrazolopyrimidine-1, PYP1)." (PMID 32555170, 2020).